IL6 (interleukin 6)
Diseases named in the same sentence as IL6 in open-access papers (continued):
Sharing a sentence is not in itself a finding about the gene and the disease.
myeloma (continued). "However, these relationships might differ in various cell and tissue types, as a study performed on multiple myeloma cells showed positive crosstalk between IL-6 and HO-1, in which HO-1 induced IL-6 expression." (PMID 39100660, 2024). "IL-6 involvement is observed in the early stages of the disease, where the myeloma interacts with the stroma and it plays a crucial role in cancer cell survival; thus, hypothetically, anti-IL-6 therapy in the early stages of the disease may have promising results." (PMID 38002012, 2023). "Signal transducer and activator of transcription 3 (STAT3) activation via IL-6 autocrine is associated with LEN-resistance, and bromodomain for CRBN binding protein/E1A binding protein p300 (CBP/EP300) inhibition can release LEN-refractoriness via the STAT3-activated myeloma cell line." (PMID 38004369, 2023). "Thus, a class switch strategy targeting the c-MYC gene and STAT3 activation via IL-6 with PI-containing therapy may be a reasonable option for LEN-refractory myeloma." (PMID 38004369, 2023). "Furthermore, IL-3 can significantly upregulate the high-affinity receptor, IL-6, in myeloma cells." (PMID 37250588, 2023). "Interestingly, a role for DSG2 in exosomes and cancer progression has been identified in squamous cell carcinoma with DSG2 promoting the secretion of exosomes that contain pro‐mitogenic cargo such as IL‐6, a known contributor to myeloma development and progression." (PMID 34245117, 2022). "Similarly, baicalein not only inhibited myeloma cell proliferation and induced apoptosis through downregulating IL-6, but also abrogated IL-6-mediated signaling cascades including JAK, STAT3, MAPK, and Akt pathways associated with the proliferation and survival of MM cells." (PMID 35153791, 2022). "Additionally, accumulating evidence indicates that ATM drives the BM-mediated resistance to chemotherapy in other hematological malignancies, such as multiple myeloma and acute lymphoblastic leukemia via upregulation of cytokines such as IL-6 or CCL3, CCL4, and GDF15." (PMID 36259537, 2022). "In addition, LEN elevated the concentration of IFN‐γ and IL‐6 in multiple myeloma patients." (PMID 36039651, 2022). "Additionally, it has been reported that myeloma cells in the BM niche take advantage of a pro-inflammatory microenvironment, especially characterized by the presence of high levels of interleukin-6 (IL-6) produced by BM stromal cells." (PMID 34829752, 2021). "Nonetheless, although IL-6 inhibition is capable of impacting myeloma growth in vitro and in preclinical models, it has been largely unsuccessful in the clinical setting; which may be unsurprising given the immune-suppressive nature of an established TME in RRMM." (PMID 33777050, 2021). "We analyzed a variety of clinical factors (gender, age, β2-MG, type of light chain, ISS stage, plasma cell number in bone marrow, peak concentration of IL-6 and CRP, and minimum value of CD4/CD8) that may be associated with CRS in patients with multiple myeloma separately." (PMID 33708205, 2021). "However, the effect of HO-1 on IL-6 expression might be dependent on cell types, since a study of multiple myeloma cells showed contrary results in which HO-1 induced IL-6 expression." (PMID 32204510, 2020). "Therefore, it can be considered an IL-6-unrelated growth factor for myeloma plasma cells." (PMID 31185596, 2019). "The main cellular source of IL‐6 in the steady state and in settings of infection, inflammation, and carcinogenesis is now widely believed to be of myeloid origin; however, normal B cells and plasma cell myeloma cells may also produce IL‐6 and bind it in an autocrine manner." (PMID 31515941, 2019). "Another hypothesis suggested that the cause might be a lack of immune regulation with increased expression of the interleukin (IL)-6 gene, a cytokine with pleiotropic effects on the immunological system and hematopoiesis, which is related to the etiology of multiple myeloma." (PMID 29728131, 2018).
myeloma (continued). "Importantly, activated platelets secrete many cytokines that are required for growth of myeloma cells including IL-6, VEGF, SDF-1α, and IGF-1, suggesting that platelets may affect the microenvironments of MM." (PMID 27852046, 2017). "Our results provide crucial information that TNIK is involved in the interleukin-6-dependent proliferation of multiple myeloma cells and inhibition of Wnt signaling involving TNIK could be a therapeutic strategy for the treatment of interleukin-6-dependent multiple myeloma." (PMID 28467797, 2017). "In addition, we examined the effect on TNIK of TNIK inhibitor KY-05009 and receptor tyrosine kinase inhibitor dovitinib and whether inhibition of TNIK suppresses the interleukin-6-induced proliferation of multiple myeloma cells." (PMID 28467797, 2017). "Notably, this VGPR rate was higher than what would have been expected for RVD alone, suggesting the possibility that targeting IL-6 could remain an interesting approach to myeloma therapy." (PMID 26871714, 2016). "IL-6 exerts dual actions: while it elicits acute phase response and stimulates proliferation or differentiation in many cell types including B cells, thymocytes, T cells and hepatocytes, it also inhibits cell growth and induces apoptosis in some myeloma cell lines." (PMID 26871479, 2016). "We next highlighted the ways in which BMAT may support MM, for example, through bioactive lipids (as a fuel source, signaling molecule, and a substrate for lipid peroxidation), and myeloma-supportive adipokines (e.g., IL-6, TNFα, MCP-1, PAI-1, IL-6, resistin, and leptin)." (PMID 27379019, 2016). "Importantly, stimulation of myeloma cells with IL-6 increased the proportion of CD45RO in the raft fractions, where CD45RO formed a complex with IL-6R, gp130, STAT3 and PKC, that could potentiate the activation of STAT3, PKC and downstream NF-κB." (PMID 25781885, 2015). "Further, IL-6 plays critical roles in the progression of non-small cell lung cancer (NSCLC), and the increased serum concentrations in patients are associated with advanced tumor stages of several tumors (e.g., multiple myeloma, renal cell carcinoma, prostate cancer, breast and ovarian cancer)." (PMID 26143636, 2015). "Moreover, we correlated them with markers of myeloma activity, such as serum levels of IL-6, IL-10, IL-15, beta-2 microglobulin (B2M), and C-reactive protein (CRP), as well as with plasma cells' infiltration and Ki-67-PI in the bone marrow, both in diagnosis and after effective therapy." (PMID 23936794, 2013). "Interestingly, the type I IFN, IFN-α, has been shown to induce IL-6 in myeloma cells." (PMID 21897875, 2011). "With regards to cancerimmunotherapy, the blockade of IL-6 has been shown to reduce tumor growth in myelomamodels.Our data suggest that the use of CDK inhibitors may block production of IL-6 andtherefore be of benefit to myeloma patients." (PMID 21559334, 2011). "Furthermore, a high-affinity fully humanized anti-interleukin 6 monoclonal antibody (mAb 1339) is available and has shown in vitro and in vivo antimultiple myeloma activity, both alone and in combination with conventional and novel agents against multiple myeloma." (PMID 22162712, 2011). "In addition, CRP has a biological role in IL-6 production and chemoresistance in multiple myeloma." (PMID 20808314, 2010). "Here, we show that c-Met signaling may be important in myeloma cell proliferation induced by IL-6." (PMID 19187270, 2009).
myeloma (continued). "The importance of cytokines (eg, interleukin IL-6, IL-1β, IL-10, and tumour necrosis factor-α) and the role of cross talk between myeloma cells and the bone marrow microenvironment in the proliferation, apoptosis and migration of myeloma cells and patient survival is becoming clearer." (PMID 18813242, 2008). "A recent clinical study has shown that the CD14+ monocytes from multiple myeloma patients could be induced to differentiate into functional DCs by culturing them with the cytokine cocktail consisting of GM-CSF, IL-4, IL-6, TNF-α and IL-1β for use in cancer immunotherapy." (PMID 18533025, 2008). "Furthermore, MM patients’ myeloma cells constitutively produce IL-6." (PMID 15970928, 2005). "Bortezomib decreases the adhesion of the myeloma plasma cell to stromal cells, which increases sensitivity to apoptosis, as well as interrupts prosurvival paracrine and autocrine cytokine loops in the bone marrow microenvironment mediated by IL-6, IGF1, VEGF and TNFα." (PMID 15655538, 2005). "Furthermore, Atiprimod inhibited signal transducer and activator of transcription (STAT) 3 activation, blocking the signalling pathway of interleukin-6, which contributes to myeloma cell proliferation and survival, and downregulated the antiapoptotic proteins Bcl-2, Bcl-XL, and Mcl-1." (PMID 15970928, 2005). "MSCs associated with multiple myeloma exhibit diminished osteogenic differentiation, elevated secretion of IL-6 and CCL2, and increased facilitation of myeloma cell proliferation and drug resistance." (PMID 40140850, 2025). "These include the interaction between myeloma cells and BM MSCs, as well as the presence of inhibitory cytokines such as TGF-β, IL-6, and IL-10, and myeloid cells." (PMID 40755766, 2025). "Interleukin-6 (IL-6), a known growth factor for MM 35, promote the tumor progression via activating the JAK-STAT3 pathway 36, facilitating the adhesion of myeloma cells to bone marrow mesenchymal stem cells 37 and obstructing dexamethasone-induced apoptosis." (PMID 40386065, 2025). "The marrow niche supplies pro-survival cues via cytokines such as IL-6, SDF-1, and BAFF, while integrin-mediated adhesion and hypoxia reinforce anti-apoptotic and drug-resistant phenotypes characteristic of myeloma persistence." (PMID 41346447, 2025). "Within the bone marrow microenvironment, adipocyte-derived IL-6 and TNFα enhance EZH2 expression in myeloma cells." (PMID 40756901, 2025). "Busulfan-conditioned human IL-6-transgenic NSG mice support the engraftment of malignant and premalignant human plasma cells, providing an effective patient-derived xenograft multiple myeloma model." (PMID 38713510, 2024). "Multiple myeloma cells secreted RNAKL and interleukin-6 (IL-6), endocytosed osteoprotegerin (OPG) to result in the elevated ratio of RNAKL/OPG, which promoted the differentiation and maturation of osteoclast precursors." (PMID 38951916, 2024). "In addition, siltuximab, a monoclonal antibody targeting IL-6, was used to treat idiopathic multicentric Castleman disease (iMCD) and cytokine release syndrome (CRS) associated with T-cell redirecting bispecific antibody therapy for relapsed/refractory multiple myeloma (RRMM)." (PMID 39664374, 2024). "When stimulated with IL-6, HIF-1α and HLA-G in the myeloma cell lines were subjected to ubiquitination and degradation." (PMID 38877399, 2024). "It has been proposed that CD138 (syndecan-1) promotes the survival of mature PCs, as well as multiple myeloma cells, by binding of anti-apoptotic factors, growth factors, and pro-survival cytokines, such as APRIL, or IL-6 through its heparan sulfate moieties." (PMID 37174629, 2023). "To study the specificity and the ability of DT2216 to degrade BCLXL, we took advantage of myeloma cell lines (HMCLs) and in particular of NAN12 cell line, which has been immortalized in presence of IL-6 from the sPCL1." (PMID 37534243, 2023).
myeloma (continued). "PG2 is characterized by high monocyte and T cell infiltration into the myeloma niche coinciding with high levels of pro-inflammatory cytokines TNF-α and IL-6." (PMID 37081258, 2023). "Apart from IL-6, BMSCs additionally produce VEGF, IGF1 or SDF-1, soluble factors that have been shown to directly or indirectly affect myeloma growth, migration and invasion." (PMID 37744361, 2023). "For instance, using immunoglobulin E (IgE) producing myeloma (U266 cells), sophorolipids extracted from Candida bombicola decreased IgE and gene expression levels of STAT3, TLR-2, and IL-6." (PMID 36441210, 2023). "Induction of myeloma cell proliferation, drug resistance to dexamethasone with TLR agonists and correlation of TLR expression with IL6 secretion indicates the important role of this inflammatory receptor in the pathogenesis of MM." (PMID 36928900, 2023). "In bone marrow mesenchymal stem cells (BMMSCs) from multiple myeloma (MM), the overexpression of PADI2 promotes the expression of interleukin-6 (IL-6) through the citrullination of histone H3R26." (PMID 37020554, 2023). "Enhanced resorption of bone material results in the release of different soluble factors such as IL-6, BAFF or APRIL that stimulate myeloma growth in a feed-forward mechanism also known as the “vicious cycle”." (PMID 35847862, 2022). "For example, in myeloma cells, BMP4 inhibits DNA synthesis depending on interleukin-6 by downregulating tyrosine phosphorylation of Stat3 induced by interleukin-6 and then inhibits tumor cell proliferation." (PMID 35401213, 2022). "Bortezomib blocked vascular endothelial growth factor (VEGF) and IL-6 secretion by endothelial cells from myeloma patients and reduced VEGF, IL-6, insulin-like growth factor-I, Angiopoietin (Ang1/Ang2) transcription." (PMID 36176763, 2022). "In serum of 57 patients, we found that IL-4, IL-6, IFN-γ, and TNF-α significantly increased in multiple myeloma compared with healthy control, especially IL-6 and IFN-γ." (PMID 35342422, 2022). "In multiple myeloma, the DNA-damaging drug doxorubicin could trigger an ataxia-telangiectasia-mutated (ATM) kinase-dependent DDR in bone marrow stromal cells, leading to increased IL-6 secretion by CAFs and resistance of myeloma cells to doxorubicin-induced apoptosis." (PMID 35488263, 2022). "These include granulocyte-macrophage colony-stimulating factor (GM-CSF) and macrophage colony-stimulating factor 1 (CSF-1) in AML, and Interleukin-6 (IL-6) in ALL and multiple myeloma (MM)." (PMID 35677056, 2022). "In NCT00911859, this randomized, open-label, phase 2 study investigated an IL6 antibody (CNTO 328, siltuximab) and its combination with velcade-melphalan-prednisone (VMP) to treat multiple myeloma." (PMID 35453676, 2022). "Curcumin is reported as an inhibitor of p-STAT3, to abrogate the IL-6-induced phosphorylation of STAT3, and inhibits the proliferation and survival of multiple myeloma cells." (PMID 34337082, 2021). "The rapid loss of cell viability of PM cells kept in conventional culture was found even in the presence of stimulating cytokines (e.g., IL6) and growth factors (e.g., IGF1), soluble factors that are known to induce the in-vitro growth of myeloma cell lines." (PMID 34201211, 2021). "It was found that IL-1Ra bound to the myeloma proliferative cells and decreased the level of C-reactive protein (CRP), a surrogate for IL-6 production." (PMID 35011853, 2021). "Studies have reported that some basal or constitutive activity of MAPK, Interleukin-6 (IL-6), insulin-like growth factor-1 (IGF-1) or other signaling pathways have been found in these myeloma cells, which can promot cell proliferation." (PMID 34579758, 2021). "We next asked if the addition of IL6, a well-known STAT3 activating cytokine in myeloma, will help improve CD38+ cell viability." (PMID 34201211, 2021).
myeloma (continued). "Interactions with stromal cells produce cytokines like IL-6, VEGF, and IGF-1 which activate the PI3K/AKT/mTOR pathway in multiple myeloma patients, initiating a signaling cascade which promotes resistance to chemotherapy and cancerous progression." (PMID 35127532, 2021). "Myeloma cells adhere to BMSC, which regulates the production of RANKL, IL-6, B-cell activating factor (BAFF), and activin A." (PMID 34201396, 2021). "In patients with myeloma, it has been shown that high-dose melphalan and ASCT results in increased plasma levels of IL-6, IL-7, and IL-15." (PMID 33777050, 2021). "In SCID mice bearing U266, BABL/c bearing MPC-11, or murine myeloma xenograft models, the antitumor activity of ISL has also be found by ISL alone or in combination with Adriamycin via blocking IL-6 signaling." (PMID 33401375, 2021). "We treated the bone marrow mononuclear cells cultured in 3D or conventional system with 30 pg/mL of IL6, which is the average serum concentration found in Stage III myeloma patients, every day for 3 days." (PMID 34201211, 2021). "The adhesion of myeloma cells to BMSC induces the secretion of several cytokines and growth factors, such as interleukin (IL)-6, and insulin-like growth factor-1 (IGF-1)." (PMID 33435539, 2021). "Most cells had decreases in Interleukin (IL)-6, Macrophage inflammatory protein (MIP)-1α, and five myeloma cell lines had a decrease in IL-8." (PMID 32903557, 2020). "Several studies have shown that IL-6 enhances VEGFA levels in various cell cancer types including gastric carcinoma, osteosarcoma, and multiple myeloma." (PMID 32318345, 2020). "Nowadays, several agents targeting IL-6, IL-6 receptor, JAKs, or STAT3 have been used in the treatment of myeloma and tested in patients with solid tumors." (PMID 33322216, 2020). "Elevated levels of interleukin (IL)-6, transforming growth factor (TGF)-β, and IL-1β in myeloma BM microenvironment promote T helper IL-17-producing (Th17) cell polarization with consequent increased of IL-17 levels in BM and peripheral blood of MM patients." (PMID 33194767, 2020). "It was reported that auranofin inhibited IL-6-induced activation of JAK2/STAT3 signaling pathway and activation of NF-κB in human multiple myeloma cell line (U266, RPM8226, and IM9)." (PMID 32695747, 2020). "Multiple myeloma cells release exosomes high in miR-21 and miR-146a that promote CAF differentiation, proliferation, and IL-6 release from MSCs." (PMID 32957712, 2020). "On the other hand, in myelomas, versican is proteolyticaly processed to the DAMP versikine, which induces the secretion of IL-1β and IL-6 by human myeloma marrow-derived macrophages (MAMs)." (PMID 31068944, 2019). "TNF-α independently promoted the proliferation of myeloma cells, and induced the expression of CCL2 in myeloma cells together with IL-6." (PMID 31334678, 2019). "Extracellular vesicles of multiple myeloma (MM) cells can stimulate secretion of cytokines, such as CXCL1, MCP1, IL6, IL-, IP-10, and CCL5 in mesenchymal stromal cells (MSCs) to promote MM cell growth and migration." (PMID 31024564, 2019). "BCL6 expression can be stimulated by cytokines such as IFN-γ, IL-6, type I IFN, IL-12, and TNF-α in myeloma or TFH cells." (PMID 30687256, 2018). "Qiu and colleagues subsequently showed that clarithromycin reduced interleukin-6 (IL-6) and tumor necrosis factor (TNF) activity in myeloma cell lines." (PMID 29743095, 2018). "PIs suppress the production of cytokines including interleukin-6 (IL-6), insulin-like growth factor 1 (IGF-1), and tumor necrosis factor α (TNFα), which can affect MSC and myeloma cell interactions." (PMID 29765356, 2018). "The cytokines IL-6 and TNF-α have been reported to be involved in the progression myeloma and hence the effect of CSL and bortezomib on the levels of these two cytokines in serum samples obtained from mice was analyzed using an ELISA kit." (PMID 29773987, 2018).